GAS5 (growth arrest specific 5)
Diseases named in the same sentence as GAS5 in open-access papers (continued):
Sharing a sentence is not in itself a finding about the gene and the disease.
GAS5 also shares sentences with these, for which no sentence is quoted: inflammatory bowel disease (6 papers); colon adenocarcinoma (3); head and neck cancer (3); laryngeal squamous cell carcinoma (3); lung diseases (3); acute myocardial infarction (2); cervical tumor (2); chronic hepatitis B (2); diffuse large B-cell lymphoma (2); hyperlipidaemia (2); infarction (2); kidney damage (2); lung squamous cell carcinoma (2); lupus nephritis (2); metabolic disorders (2); myocardial ischemia (2); pleural mesothelioma (2); sarcoidosis (2); Abdominal obesity (1); airway hyperresponsiveness (1); allergic asthma (1); aortic aneurysm (1); Aortic dissection (1); Arterial stenosis (1); artery disease (1); Arthritis (1); bone tumors (1); cardiomyopathy (1); cerebrovascular disease (1); cervical squamous cell carcinoma (1).
A further 49 diseases each share a sentence with GAS5 in 1 paper.